RNU6-159P (RNA, U6 small nuclear 159, pseudogene)
Gene: Small nuclear RNA gene on chromosome 16 (27,863,251 to 27,863,356, forward strand). Ensembl gene ENSG00000212382.
Homologues: Orthologues: chimpanzee U6 (100% identical), macaque U6 (95% identical), pig U6 (75% identical). Paralogues in human: RNU6-1243P (84% identical), RNU6-1270P (83% identical), RNU6-1152P (82% identical), RNU6-140P (82% identical), RNU6-24P (82% identical), RNU6-43P (82% identical), RNU6-49P (82% identical), RNU6-939P (82% identical), RNU6-1060P (81% identical), RNU6-1216P (81% identical), RNU6-1249P (81% identical), RNU6-1309P (81% identical), and 1289 more.